IFNG (interferon gamma)
Diseases named in the same sentence as IFNG in open-access papers (continued):
Sharing a sentence is not in itself a finding about the gene and the disease.
cancer (continued). "Although IFNγ is considered to be antitumorigenic, its induction of PD-L1 transcription in cancer cells might positively correlate to anti-PD-1 or PD-L1 therapy response in established tumors." (PMID 30158932, 2018). "The clinical significance of IFNγ expression in human cancer has been observed." (PMID 30039553, 2018). "Based on our result, IFNγ might be an effective anti-cancer drug for tumors that lack a high level of expression and/or activation of ERK, and/or express a certain basal level of STAT1 that can be activated." (PMID 29855346, 2018). "Furthermore, many cancers and healthy cells upregulate PD-L1 expression in response to inflammatory cytokines, such as interferon-gamma (IFN-γ)." (PMID 28515726, 2017). "While no anti‐IFNγ therapy has been tested in humans so far, some studies using antibodies against this cytokine have shown some successes in interfering with cancer‐induced muscle loss in mice." (PMID 28264935, 2017). "IFNγ has been shown to stimulate PD‐L1 expression downstream of Stat1 in several cancer cells." (PMID 27932443, 2017). "Interferon-γ (IFNγ) has been shown to induce IDO1 in a variety of malignancies." (PMID 29156701, 2017). "Additionally, however, we noted a specific set of genes encoding chemokines and cytokines, namely CCL4, CCL8, CXCL10, CXCL11, IFI44L, IDO1, and IFNG that were upregulated in 9p CNG cancers." (PMID 29212506, 2017). "Our study uncovers the complexity behind cancer cell responses to IFNγ." (PMID 28428785, 2017). "Thus, from these initial experiments we decided to go on to compare the maturation cocktail containing the GMP-grade poly I:C Hiltonol© in combination with IFNγ and R848, with TNFα alone that has been used by us and others in earlier cancer DC vaccine trials." (PMID 28601925, 2017). "It is hypothesized that the IFNγ-inducibility of IRF1 predicts better responsiveness to anti-cancer therapy." (PMID 27966453, 2017). "Indeed, IFNγ has been identified as a mediator of cell cycle regulation in both normal and cancer cells." (PMID 28526810, 2017). "IFNγ has been used in a wide variety of clinical indications including cancers." (PMID 28526810, 2017). "Enhancement of IFNγ expression may have a positive role in immune suppressed cancer patients by providing them protective immunity against infections." (PMID 28793897, 2017). "Thus, in future cancer DC vaccine clinical trials the maturation of the DC should be performed in the presence of IFNγ, R848, poly I:C, and LPS." (PMID 28601925, 2017). "These included genes involved in cell death and survival processes (BCLAF1, CFLAR, CASP1, and XIAP), genes associated with proliferation-driving transcription or cancer (KLF4, LEF1, SOX4, ID3), and genes associated with inflammation (CD28, CCR7, CX3CR1 and IFNG)." (PMID 28407008, 2017). "The expression of PDL1 was upregulated after IFNγ exposure in the cancer cell lines." (PMID 27631416, 2016). "Notably, the overexpression of LTβ in cancer cells significantly reduced the expression of iNOS, TNFα and IFNγ in parenchymal MAMs by 35%, 79% and 25%, respectively, implicating LTβ in polarization of MAMs towards the M2 state." (PMID 27203741, 2016). "Therefore, CXCR6/CXCL16 co-stimulatory interactions represent a potential target for manipulation in cancer therapies, where a boost in the Th1 IFNγ response is desired." (PMID 27471636, 2016). "This suggests that the downregulation of iNOS, TNFα and IFNγ in MAMs in our model may occur through a direct interaction between LTβ on cancer cells and the LTβR on MAMs." (PMID 27203741, 2016).
cancer (continued). "Moreover, it has also been reported that IL17, a pro-inflammatory cytokine produced by Th17 subsets upon stimulation by IFNγ, promotes immune-suppressive chronic inflammation that can be present in both auto-immune diseases and cancer." (PMID 27752361, 2016). "According to previous studies, TNFα induced NF-κB signaling could counteract TNFα-induced apoptosis while IFNγ could inhibit NF-κB activation and the expression of downstream apoptosis inhibitors, finally sensitizing the cancer cells to TNFα treatment." (PMID 27342639, 2016). "Interferon gamma (IFN-γ) has antitumor and antiproliferative effects, and previous studies indicated IFN-γ +874T/A (rs2430561) polymorphism were related to the risk of many types of cancer." (PMID 27015189, 2016). "In spite of the decreased expression of several proteins, B1 AMCE could also up-regulates several proteins such as interferon-gamma (IFN-γ) and monokine induced by interferon-γ (Mig) which underlines its favourable criteria as anti-cancer agent." (PMID 27558166, 2016). "However, because several studies have shown that interferon treatment has severe toxic effects there is reluctance to use IFNγ in cancer patients." (PMID 26452036, 2015). "There is excitement over the potential of EZH2 inhibitors to treat cancer, and their ability to augment protective cytokine pathways (e.g. IFNγ) could boost efficacy." (PMID 26030458, 2015). "Furthermore, a recent study showed that the combined action of TNFα and IFNγ is necessary for the control of a range of murine and human tumors by driving cancer cells into senescence." (PMID 26635798, 2015). "Consequently, several biomarkers have been reported to reflect the link between inflammation and cancer, such as interferon-gamma/interleukin-4 ratio and inflammation-based prognostic score (Glasgow prognostic score) based on CRP and albumin levels." (PMID 25885254, 2015). "TRAIL and IFNγ are promising anti-cancer cytokines and it has been shown that IFNγ may sensitize cancer cells to TRAIL." (PMID 25428727, 2014). "Activation of signal transducer and activator of transcription 1 (STAT1) in cancer cells by the increased interferon gamma (IFN-γ) production in immune cells played an important role in downregulating HER2 in cancer cells upon engagement of immune cells by trastuzumab." (PMID 24693969, 2014). "However, administration of recombinant IFNγ had disappointing outcomes in various cancer immunotherapy trials possibly due to its toxicity." (PMID 24363024, 2014). "Indeed, pro-inflammatory cytokine IFNγ has been shown to contribute to the pathogenesis and development of gastric metaplasia and cancer." (PMID 24069395, 2013). "The production of TNFa and IFNg are both reduced in STIM1/STIM2 double knockouts as compared to wild types, providing insight into the mechanism of the immunodeficiency of deficient SOCE in CD8+ T cells against cancer cells." (PMID 24000152, 2013). "It is also possible that IFNγ itself offered some indirect anti-cancer protection." (PMID 23056548, 2012). "So while focusing on IFNγ regulation of structural elements of the epithelial barrier we should not overlook IFNγ-Fyn-Hakai activity in the contexts of cell signalling, gene regulation and cancer." (PMID 22715382, 2012). "IFNγ inhibits the growth for both types of cells and may be prototypic of agents that simultaneously hit cancer and stroma cells." (PMID 23284277, 2012). "Cancer cell adhesion following AngII stimulation was also increased (2 fold) when endothelial cells were pre-activated for 24 hrs with pro-inflammatory cytokines (IFNγ and TNFα)." (PMID 22536420, 2012). "IFNγ can exert anti-cancer effects in several different ways." (PMID 21674047, 2011). "Based on these data, we hypothesized that both stellate and cancer cells may be targets of antiproliferative effects of IFNγ." (PMID 21310022, 2011).
cancer (continued). "Increasingly sensitive measures of systemic cellular immune response, such as the γ-interferon (IFNγ) enzyme-linked immunospot (ELISPOT) and tetramer assays, may facilitate the early clinical development of cancer vaccines." (PMID 20109236, 2010). "Cocktail 1 was designed as in a previous reported cocktail, where the combination of poly I:C, IFNα, IFNγ, TNFγ and IL-1β showed very potent IL-12p70 stimulating properties compared to the standard DC cocktail used for DC based cancer vaccines, containing IL-6, TNFα, IL-1β and PGE2." (PMID 20663192, 2010). "Notably, our findings suggested that low AR activity may reflect higher immune infiltrates and IFNγ immune signature activity in the TME, which is also associated with improved response to ICB treatment in various cancers." (PMID 41486951, 2026). "Inhibition of the IFNγ signaling pathway promotes an immunosuppressive micro-environment, which in turn mediates immune escape, which may be one of the mechanisms of its malignant pro-cancer properties." (PMID 40960294, 2025). "While our work establishes a link between IFNγ expression and CTL cytotoxicity, further studies are needed to clarify whether IFNγ enhances lytic function through blocking IFNγ release from CTLs and in vivo autoimmune or cancer animal models are needed to verify their functional difference." (PMID 40725272, 2025). "Notably, the GZMA CD4 T cell subset exhibited elevated expression of genes associated with effector and cytolytic functions in CD4 T cells, including GZMA, GZMH, GZMM, and PRDM1, while also showing moderate expression of anti-cancer-related genes such as IFNG, PRF1, and TNFSF10." (PMID 40959273, 2025). "Additionally, the knockdown of PD-L1 mRNA expression in cancer cells exhibited sustained efficacy, with lipid-siPDL1s demonstrating robust RNAi effects even in the presence of elevated PD-L1 mRNA expression following prolonged IFNγ stimulation." (PMID 40001596, 2025). "In addition, they induce the upregulation of PD-L1 and HLA-DR expression in cancer cells via IFNγ." (PMID 39962623, 2025). "In addition to its well-recognized role in orchestrating antitumor immune responses, prior experimental evidence indicates that IFNG can modulate ferroptotic susceptibility by downregulating SLC7A11 expression and enhancing lipid peroxidation in select cancer contexts." (PMID 40868287, 2025). "While several reports of IFNγ pathway somatic mutations were found in post-ICB treatment patients, it is often unclear whether those mutations can be present before ICB, and if they affect overall survival of cancer patients." (PMID 39746898, 2025). "Additionally, the SFV/IFNγ group exhibited the lowest significance for neutrophil and granulocyte migration which was induced by cancer cells and may indicate the inhibition of cancer cell-induced processes." (PMID 40547518, 2025). "Importantly, HLA class II expression on cancer cells increases due to IFNγ signaling." (PMID 39928678, 2025). "Interestingly, IFNγ secretion tended to be improved in response to the TGFβ neutralizing antibody, suggesting that TGFβ was secreted and activated immunosuppression when PBMCs and cancer cells were cocultured." (PMID 39105882, 2024). "It is, however, worth noting that in most cancer types, the anti-tumoural activities of IFNγ largely outweighs it’s pro-tumoural effects, and indeed increased IFNγ expression is amongst the strongest positive prognostic indicator of improved patient survival across a broad range of cancer types." (PMID 38464388, 2024). "This, therefore, raises the exciting prospect of combining iNOS inhibitors (or other strategies that target iNOS+ MDSCs) with IFNγ-based cancer therapies, which may show potentiation by removing the pro-tumoural aspect of IFNγ while preserving the anti-tumoural functions." (PMID 38464388, 2024).
cancer (continued). "Therefore, in this context, IFNγ may be contributing to chronic inflammation, ROS production, and carcinogenesis, but further studies would be required to confirm if this is the cancer driving pathway." (PMID 39588838, 2024). "However, it was unclear whether the and/or case, single positive, or double positive is more useful in controlling cancer, so we compared them in this study based on four criteria: IFNγ+ and/or 4-1BB+, IFNγ+, 4-1BB+, and double-positive (IFNγ+4-1BB+)." (PMID 38550601, 2024). "Thus, relieving the blockade on IFNγ signaling that upregulates the checkpoint ligand could be another reason why cancer cells choose to repress SOCS1 expression by diverse mechanisms." (PMID 38415248, 2024). "In cancer studies, comprehensive pathway analysis shows that PANoptosis score positively correlates with several pathways associated with immune and inflammatory responses in pan-cancer, including IL6-JAK-STAT3 signaling, the interferon-gamma (IFN-γ) response, and IL2-STAT5 signaling." (PMID 38169587, 2024). "Also, the expression of effector T cell activation markers (IL-2, GZMB, IFNG) in edT cells were significantly lower after co-culture with T cell-resistant (R) as compared to -sensitive (S) cancer cells, indicating decreased T cell effector functionality and thus impaired PDAC cell killing." (PMID 38654067, 2024). "When T-cells are incubated with cancer cells, we observe T-cell-intrinsic cytokine secretion, which to a certain extent, may predict in vivo immune toxicity by level of hyperproduction of TNFα, IFNγ, MCP-1, and others." (PMID 39594640, 2024). "DUX4 expression in several cancer cell lines was sufficient to prevent the induction of MHC-I expression in response to interferon gamma (IFNγ); however, it was unclear whether this represented an activity restricted to MHC-I or a broader activity of DUX4 in regulating protein expression." (PMID 37747887, 2023). "Notably, in the PD-1/PD-L1 cancer immunotherapy pathway, CD274, the gene that transcribes PD-L1, PDCD1LG2, the gene that transcribes PD-L2, and PTPN11, the gene that encodes SHP2 are all predicted to be activated by IFNγ in astrocytes." (PMID 37828609, 2023). "Trm cells can release effector molecules and cytokines, such as interleukin-2, interferon-gamma (IFN-γ), tumour necrosis factor-α, and granzyme B. Sustained high expression of these factors may enable Trm cells to rapidly and strongly respond against cancer cells." (PMID 36869093, 2023). "Our insights into determinants of peptide abundance changes with IFNγ exposure could be useful to improve the design of cancer vaccines or TCR engineered therapies as it could enable the more accurate selection of peptides likely to be presented on patient tumors." (PMID 37991387, 2023). "Furthermore, GSEA also revealed the hallmarks of malignant tumors, including inflammatory response, interferon gamma response, epithelial-mesenchymal transition, angiogenesis, focal adhesion and KRAS signaling, were significantly enriched in LGGs with higher risk score." (PMID 37488496, 2023). "Indeed, in patients with a persistent or heavy disease burden, T cells are often identifiable with tetramers, but not through stimulation assays that measure interferon-gamma (IFN-γ) or interleukin-2 (IL-2) secretion as a means of detecting the presence of cancer-specific T cells." (PMID 37287968, 2023). "In showing that NKG2D expression is correlated with a IFNγ response while at the same time being associated with reduced survival in patients as well as in a mouse model, our studies highlight the existence of antagonistic effects of NKG2D during cancer progression." (PMID 36980678, 2023). "The IFNγ ssGSEA scores were significantly negatively correlated with PA combined, synthesis, and hypusine ssGSEA scores in seven (r range: −0.42 to −0.17), six (r range: −0.45 to −0.25), and 12 (r range: −0.38 to −0.15) cancer types, respectively (FDR q < 0.25)." (PMID 36052016, 2022).
cancer (continued). "Together, these results suggest that BAY1082439 treatment may convert the PTEN-loss induced cancer cell-intrinsic immuno-suppression to immuno-stimulation by upregulating IFNα and IFNγ pathways, increasing cancer cell antigen-presentation, and releasing T cell attractive chemokines." (PMID 35013322, 2022). "Interferon-gamma (IFNγ) secreted by CD8+ T cells could stimulate the ferroptosis of cancer cells." (PMID 35874826, 2022). "Thus, IFNγ is likely a key mediator of efficacy for cancer immunotherapy." (PMID 36551577, 2022). "‘Cancer immunoediting’, the process whereby the human immune system destroys cancer cells within the body, is thought to rely upon a variety of cytokines (for example, IFNγ) and cell types (such as NK cells) that could be affected by JAK inhibition." (PMID 35504889, 2022). "However, a concurrent limitation with using this mouse model of metastatic human cancers is the inability to determine the efficacy of PD-1/PD-L1 blockers in combination with IFNγ or assess the role of immune cells in mediating the effects of IFNγ in combination with chemotherapy." (PMID 35459800, 2022). "However, in cancer context, TGFβ is responsible for promoting the generation of pro-tumoral type N2 neutrophils, whereas type IFNβ and IFNγ might favor anti-tumoral type N2 neutrophils." (PMID 36311783, 2022). "Impaired IFNγ production may be a main contributor to postoperative formation of cancer metastases and understanding the changes in NK cell biology responsible for impaired IFNγ is essential for the development of effective perioperative immunotherapeutics for patients undergoing cancer surgery." (PMID 36498937, 2022). "Lunasin exhibits immunomodulatory activity against cancer, specifically through combining with cytokines interleukin-2 (IL-2) and interleukin-12 (IL-12); this combination has a synergistic effect that stimulates natural killer (NK) cells to enhance interferon gamma (IFNγ) production." (PMID 36076946, 2022). "Interestingly, our sequencing data show that WARS, which can protect cancer cells from IDO-mediated tryptophan depletion, is highly upregulated on mRNA level in the presence of IFNγ in all cell lines, underlining the pro-inflammatory activity of IFNγ in this context." (PMID 35003017, 2021). "Additionally, immunotherapy activated CD8+ T cells can induce ferroptosis in cancer cells by interferon gamma-mediated downregulation of the two subunits of system Xc−, solute carrier family 7 member 11 (SLC7A11) and SLC3A2, leading to a decrease in the antioxidant capacity of cancer cells." (PMID 33499222, 2021). "Importantly, an IFNγ‐induced PD‐L1high/MHC class I moleculeshigh/NKG2D ligandslow phenotype is optimal for cancer cells to escape NK cells, since NK cells are inactivated by PD‐L1 and MHC class I molecules, while they are activated by NKG2D ligands on cancer cells." (PMID 33491334, 2021). "Enterococcus hirae could translocate from the small intestine to secondary lymphoid organs and increase the intratumoral CD8/Treg ratio, while Barnesiella intestinihominis could promote the infiltration of interferon-gamma (IFN-γ)-producing γδT cells in cancer lesions." (PMID 34361904, 2021). "In addition, T cells and interferon-gamma (IFN-γ) sensitize cancer cells to ferroptosis." (PMID 35174170, 2021). "Interferon gamma (IFN-γ), produced by T-cells and other immune cells, is essential for controlling proliferation of transformed cells, induction of apoptosis and enhancing human leukocyte antigen (HLA) expression, thereby increasing immunogenicity of cancer cells." (PMID 34335558, 2021). "Furthermore, MSCs decrease NK cells’ ability to express IFNγ, weakening their anti-cancer activity." (PMID 33472580, 2021).